AR (androgen receptor)
Diseases named in the same sentence as AR in open-access papers (continued):
Sharing a sentence is not in itself a finding about the gene and the disease.
prostate carcinoma (continued). "This signaling pathway undergoes significant genomic alterations, and more β-catenin nuclear translocalization and co-localization with AR in CRPC compared to hormone naïve primary prostate cancer, which shows no alterations and less translocation." (PMID 28846663, 2017). "Such antiproliferative effect of exendin-4 on prostate cancer was not via androgen receptor, but through the inhibition of extracellular signal–regulated kinase-mitogen-activated protein kinase (ERK-MAPK) phosphorylation via GLP-1R." (PMID 27661113, 2017). "AIM1 mRNA was expressed in the prostate cell lineage, in normal prostate epithelial cells, and in multiple prostate cancer cell lines independent of their androgen receptor status." (PMID 28747635, 2017). "SRF has also recently been associated with androgen receptor (AR) hypersensitivity; where a negative feedback loop exists between SRF expression and AR transcriptional activity in the setting of castrate-resistant prostate cancer." (PMID 28249598, 2017). "Lupeol caused elicitation of apoptosis through G2/M arrest (PC3 cells) and reduction of β-catenin signaling in AR-negative human prostate cancer (DU145 cells)." (PMID 28846663, 2017). "The androgen receptor (AR) plays a crucial role in normal physiology, development and metabolism as well as in the aetiology and treatment of diverse pathologies such as androgen insensitivity syndromes (AIS), male infertility and prostate cancer (PCa)." (PMID 28165461, 2017). "Moreover, miR-221/222 was involved in the progression from hormone-sensitive to castration-resistant prostate cancer by downregulating HECTD2 and RAB1A, which subsequently led to reprograming of AR signaling, and activation of EMT and new cyclins." (PMID 28261196, 2017). "However, the result showed a positive correlation (odds ratio: 3.24, confidence interval: 1.77-5.96) between the AR and DDB2 in human prostate cancer tissues; it contradicted in vitro conclusion of DDB2-degrading AR." (PMID 28212551, 2017). "We found that AURKA expression correlates with the AR level in hormone-naïve prostate cancer specimens, suggesting the AURKA expression may play a role in the early progression of prostate cancer." (PMID 29269934, 2017). "We have recently demonstrated AR exerts its oncogenic effects in prostate tumors by down-regulating the type II receptor of TGF-beta, hence attenuating the tumor-suppressive activity of TGF-beta pathway in prostate cancer." (PMID 27741511, 2017). "Genetic or pharmacological blockage of Src sensitizes prostate cancer cells towards CYT997 regardless of AR expression." (PMID 28606127, 2017). "Directly derived from the Pten-Pb-Cre mouse prostate cancer model, the PTEN-P2 and PTEN-CaP2 cell lines were chosen as an initial in vitro prostate cancer model to test the efficacy of DR17 that targets the PTEN/PI3K/AKT and AR pathways." (PMID 28350865, 2017). "Recently, PR has been reported to be highly expressed and an independent negative prognostic factor for clinical trials for prostate cancer thereby making inhibition of PR a potential benefit of an approach that blocks both AR NTD and PR." (PMID 28306720, 2017). "It has been suggested that 10 to 25% of advanced AR-positive prostate cancers will become AR-negative NEPC2,7." (PMID 29269934, 2017). "Our previous work also indicated that MEIS1 functions as a negative AR regulator and inhibits the ligand-dependent growth of certain kinds of prostate cancer." (PMID 28270206, 2017). "While AR-negative DU-145 cells also expressed CXADR, PC-3, another AR-negative prostate cancer cell line, did not." (PMID 28074864, 2017). "AR-positive prostate cancers and AR-negative NEPCs seem to have, at least in some cases, the same clonal origin because they share the same molecular alterations, such as ERG rearrangements." (PMID 29269934, 2017).
prostate carcinoma (continued). "During prostate cancer progression, androgen-deprivation therapy is no longer effective, resulting in castration resistant prostate cancer (CRPC) in which the AR signaling is reactivated upon AR gene amplification, mutations, or truncations." (PMID 28415632, 2017). "Our study demonstrated for the first time that CPA enhances TRAIL-induced apoptosis in AR-negative, androgen-independent prostate cancer cells via DR5 up-regulation." (PMID 28270124, 2017). "Considering the co-occurrence of aberrant AR and SEMA3C in advanced prostate cancer, we speculate that restored AR signaling in advanced PCa drives SEMA3C expression which in turn propels PCa progression." (PMID 28038451, 2017). "However, knocking down LSD1 did not upregulate metastasis-associated miRNAs in either LnCAP cells or in RWPE-1 cells overexpressing AR, HOXC6 or NKX2-2, suggesting that other co-factors mediate the transcriptional repression of miRNAs in prostate cancer." (PMID 28397780, 2017). "Besides, PCAT1 cooperates with AR and LSD1 and is necessary for their gathering at the enhancers of two androgen late-response genes involved in prostate cancer tumorigenesis." (PMID 28989584, 2017). "Most prostate cancers are androgen-dependent (with androgen receptor (AR) expression) adenocarcinomas, which possess a glandular formation, and can produce prostate-specific antigen (PSA) under the regulation of AR activity." (PMID 28846663, 2017). "However, ING3 knockdown also reduced the growth and migration of AR-negative prostate cancer cells, DU145 and PC3, indicating its role in AR-independent pathways." (PMID 28511652, 2017). "Another limitation of our study is that we used androgen receptor-negative cell lines, which are commonly used in prostate cancer studies." (PMID 28455956, 2017). "Firstly, we examined the significance of three hormone receptors: AR, ESR1, ESR2 in the biology of prostate cancer regarding the effect of their expression on tumor recurrence according to patient’s age (four age groups: ≤50, 51–60, 61–70, 70> years old) through disease-free survival (DFS) analysis." (PMID 29206234, 2017). "In the clinical setting, inhibition of AR activity frequently leads to the development of castration-resistant prostate cancer, a condition with no curative treatment options." (PMID 28415728, 2017). "Regardless of these discrepancies, in all cases, AR promotes the activation of FGFR in prostate cancer cells, which results in phosphorylation of FRS2 and activation of the downstream Ras/Raf/MEK/ERK signaling pathway." (PMID 28077787, 2017). "For example, enhanced expression of FKBP51 can stimulate AR in prostate cancer and thus drive malignancy, while as a negative regulator of Akt1 FKBP51 is important for the action of chemotherapeutic agents in pancreatic cancer cells." (PMID 29206196, 2017). "Although some reports have been demonstrated that androgens and AR play an active role in inducing EMT, others have shown that EMT induction is due to androgen deprivation or low AR content both in in vivo and in vitro prostate cancer settings." (PMID 28430640, 2017). "As such, decreased AR and 5αR2 along with increased 5αR1 in tumors may promote PIN and prostate cancer development, thus warranting further investigation." (PMID 28493878, 2017). "While prostate cancer cells may evolve mechanisms to bypass AR signaling, the growth of CRPC has in the majority of cases been shown to be dependent on sustained AR signaling despite a castration level of testosterone." (PMID 28561752, 2017).
prostate carcinoma (continued). "In agreement with in vitro observations, analysis of The Cancer Genome Atlas (TCGA) data (n = 498) and a prostate cancer tissue microarray (n = 256) show that ING3 levels are higher in aggressive prostate cancers, with high levels of ING3 predicting shorter patient survival in a low AR subgroup." (PMID 28511652, 2017). "We speculate that regulation of the AR-IRE1α-CREB3L4 pathway in the presence of androgen, may maximize the effect of androgen on proliferation of prostate cancer cells." (PMID 28338058, 2017). "The relationship between the expression of NRIP, AR and DDB2 and the pathological sub-types of prostate cancer, we found that a specific pattern of high expression of NRIP and AR and simultaneous low expression of DDB2 was detected more frequently in cribriform tumors than in non-cribriform tumors." (PMID 28212551, 2017). "Collectively, AR expression is significantly higher in our prostate cancer tissues than non-neoplastic tissues." (PMID 28212551, 2017). "PC-3 and DU145 are two androgen-independent prostate cancer cell lines and also often characterized as AR negative." (PMID 28270124, 2017). "In prostate cancer cells, Cdk5 promotes cell growth in an androgen receptor (AR)- independent way and maintains high AKT kinase activity, which is known to correlate with prostate cancer progression and considered as a critical growth-promoting pathway in prostate cancer cells." (PMID 28288624, 2017). "In prostate cancer, the efficacy of PD-0332991 was dependent on the Rb status, not on the androgen receptor." (PMID 28472136, 2017). "We then verified the activity of the polymorphic regulatory region containing the 7p14.3 variant with an in vitro luciferase assay in two model systems, AR-negative (PC-3) and AR-positive (LNCaP) prostate cancer cells." (PMID 28663546, 2017). "Our further study demonstrated that CPA enhances TRAIL-induced apoptosis in AR-negative, androgen-independent prostate cancer cells by up-regulation of DR5." (PMID 28270124, 2017). "There is a clear potential for CYT997 to be used in all prostate tumors carrying AR or not and perhaps all clinical stages of prostate cancer since it can greatly inhibit nearly all prostate cancer cell lines." (PMID 28606127, 2017). "Given the implication of both AR and SEMA3C in prostate cancer development, in combination with the discovery of ARBSs within the SEMA3C locus, we hypothesized that SEMA3C is a transcriptional target of the androgen receptor." (PMID 28038451, 2017). "Loss of 11β-HSD2 protein in AR-expressing LAPC4, VCaP and MDA-PCa-2b prostate cancer cell lines (but not an AR-negative prostate cancer cell line) was observed with enzalutamide treatment, while no consistent effect on 11β-HSD1 was detectable." (PMID 28191869, 2017). "To our surprise, we noted that pretreatment of AR-negative, androgen-independent prostate cancer PC-3 and DU145 cells with anti-androgen CPA greatly enhanced their sensitivity to TRAIL." (PMID 28270124, 2017). "Mechanistically, it appears that androgen induction of VEGF is regulated through AR complex formation with Sp1 in the core promoter region in prostate cancer cells and not via ARE binding sites in the distal VEGF promoter." (PMID 28394264, 2017). "We have demonstrated that increased CXCR7 in the absence of AR signaling potentiates EGFR-mediated mitogenic signaling in prostate cancer cells." (PMID 28596572, 2017). "ARv567es mRNA is made through skipping of exons 5–7 of the AR pre-mRNA and is only expressed within prostate cancer (and not the normal prostate)." (PMID 28382513, 2017). "The assay showed that C4-2 prostate cancer cells have a high level of AhR and AR promoter activity in the absence of inhibitor treatment." (PMID 28671964, 2017). "Treatment of mice with this peptide encapsulated in PEGylated liposomes inhibited the growth of an AR negative prostate cancer cell line without toxicity." (PMID 28264478, 2017).
prostate carcinoma (continued). "Therefore, the investigation of the relationship between AR signalling and SGTA function in canine prostate cancer allows a better understanding of the mechanisms of formation of androgen-independent prostate cancer beyond the species." (PMID 28599655, 2017). "PC-3 and DU-145 cells are androgen receptor (AR)-negative prostate cancer cells derived from bone and brain metastasis of PCa cells, respectively." (PMID 27191743, 2016). "First, we observed that KLF4 overexpression in AR-negative prostate cancer cell lines increased miR-1 expression." (PMID 27991915, 2016). "Our results suggest that DANCR could be a potential target for preventing prostate cancer metastasis, and knockdown DANCR may lessen the potential side effect of AR inhibitor." (PMID 27191265, 2016). "It is possible that upon increased DNAH8 expression during prostate cancer progression, DNAH8 could increase AR and/or AR cofactor nuclear accumulation and foster androgen-independent AR activation." (PMID 27363033, 2016). "Interaction between androgen receptor and p52 factor (engaged in noncanonical NF-κB pathway activation) promotes prostate cancer cell growth, protects from apoptotic cell death, and influences expression of androgen receptor dependent genes." (PMID 27975057, 2016). "In particular, drugs are needed that target hormone-refractory prostate cancer cells regardless of differentiation state, with various levels of androgen receptor (AR) and prostate-specific antigen (PSA) expression." (PMID 27054343, 2016). "In prostate cancer, USP22 overexpression lead to increased androgen receptor splicing." (PMID 27057639, 2016). "In contrast, cells that do not rely on the AR for proliferation such as PC-3 prostate cancer cells and 3T3-L1 preadipocytes were minimally impacted by the combination of ACLYi and ENZ (denoted hereafter as Combo)." (PMID 27248322, 2016). "This implies that the CRPC associated increased PC-1 expression may not respond due to AR variants that lack the hinge region being able to potentially escape PC-1-mediated degradation, thus maintaining high transcriptional activity and contributing to prostate cancer progression." (PMID 27835608, 2016). "Here we describe a mechanism by which the AR can be targeted for destruction in prostate cancer cells, in a manner that does not directly inhibit the AR itself or androgen metabolism, using MDM2 antagonists." (PMID 27729622, 2016). "In the present work we aimed to explore whether Brachyury is a molecular driver of the major mechanisms of prostate tumor therapy-resistance, namely AR, EMT, NEtD and stemness, in prostate cancer cells treated with docetaxel and cabazitaxel." (PMID 27049720, 2016). "In order to reflect the diversity of castration resistant prostate cancer, the anticancer effect of Rhiz was explored using a panel AR/AR-V7 positive and AR negative CRPC cell lines." (PMID 27626485, 2016). "In summary, we have defined and characterized a human osteonectin promoter (hON-522E) that contains only positive transcriptional regulatory elements and is highly active in AR-negative and metastatic prostate cancer cells." (PMID 27054343, 2016). "Whereas DNAH8 protein abundance appeared higher in AR-expressing compared to non-AR-expressing prostate cancer cells lines, this paralleled androgen-dependent DNAH8 mRNA expression and AR recruitment to the DNAH8 promoter." (PMID 27363033, 2016). "Our present data indicate that CCL2 induces prostate cancer cell migration in vitro not only under ADT conditions but also without the suppression of androgen/AR signaling." (PMID 26701731, 2016).
prostate carcinoma (continued). "Numerous cofactors of the AR have been described in prostate cancer, but a coregulator that exclusively regulates the AR has not been described so far." (PMID 27583472, 2016). "SUMO3 has also been found to enhance Androgen Receptor (AR) transcription independent of sumoylation mechanism in prostate cancer cells." (PMID 27767176, 2016). "Alternatively, if AR promotes RCC growth, then second-generation anti-androgen therapies that have been developed for prostate cancer might prove useful in treating RCC." (PMID 26814892, 2016). "Similarly to these studies that highlight the cell-context-dependent regulation of EMT by AR, a previous study reported that Snail overexpression induced neuroendocrine prostate cancer (NEPC) differentiation in prostate cancer cells." (PMID 27409172, 2016). "We next examined the effects of VT-464 and abiraterone on the AR reporter (FKBP51-ARE-luciferase) activity with overexpression of wild-type AR, two mutant ARs, and AR-V7 in AR-negative PC3 prostate cancer cells." (PMID 27748439, 2016). "RNF6 did not change AR stability but rather its activity and it is required for prostate cancer cell growth." (PMID 27057639, 2016). "Resurgent activity of androgen receptor (AR) and the up-regulation of coactivator protein p300 and cAMP response element-binding protein (CBP) resulted in aggressive phenotypes and hormone therapy failures in prostate cancer." (PMID 27529277, 2016). "We should, however, mention that studies of PDE4D7 expression in the VCaP prostate cancer cell line implied that it was not directly regulated by AR." (PMID 27683107, 2016). "In this study we used an AR antagonist and several PI3K-pathway inhibitors targeting various nodes of the complex signaling pathway and tested their as single agents or in combination in several prostate cancer cell lines." (PMID 27783994, 2016). "In prostate cancer, FISH was applied to study CNA of AR, BRCA1, MYC, and PTEN." (PMID 26980749, 2016). "Initially, CCL2 was reported to promote prostate cancer metastasis through the recruitment of macrophages using PC-3 cells that did not express AR." (PMID 26701731, 2016). "In vitro reporter assays revealed that the hON-522E promoter is highly active in androgen receptor negative and metastatic prostate cancer and bone stromal cells compared to androgen receptor-positive prostate cancer cells." (PMID 27054343, 2016). "The elevated expression of SIAH2 may not only increase the transcriptional activity of AR, but also potentially reduce EAF2 protein level and its potential tumor suppressive activity, further promoting malignant growth of prostate cancer." (PMID 27058417, 2016). "This work provides evidence that the intrinsically disordered NTD of AR is druggable and that SINT1 analogs may provide a novel scaffold for drug development for the treatment of prostate cancer or other diseases of the AR axis." (PMID 27576691, 2016). "Sensitization of the prostate cancer cell lines LNCaP (androgen-receptor positive) or PC3 (androgen-receptor negative) with BaxM159 significantly reduced the half-maximal effective concentration (EC50) of mitoxantrone by 40% and 30%, respectively." (PMID 27636991, 2016). "However, prostate cancer patients receiving androgen deprivation therapy often relapse and develop castration-resistant prostate (CRPC), which still relies on the AR pathway for growth." (PMID 27363033, 2016). "In contrast with the anti-proliferative and pro-apoptotic roles of AR in non-malignant prostate epithelial cells, most prostate cancer cells express AR and are somewhat dependent on AR signaling for growth and proliferation." (PMID 27203692, 2016). "PC-1 may also act by blocking AR activity to increase AKT activity and promote prostate cancer progression." (PMID 27835608, 2016).